NLRP3 (NLR family pyrin domain containing 3)
Diseases named in the same sentence as NLRP3 in open-access papers (continued):
Sharing a sentence is not in itself a finding about the gene and the disease.
systemic lupus erythematosus (continued). "The NLRP3 has been found to serve as a key driver of several autoimmune conditions including both RA and systemic lupus erythematosus (SLE)." (PMID 32477105, 2020). "Antagonists of TLR-7,−8, and−9 inhibit NLRP3 inflammasome-related pathways in NZBW F1 lupus model mice, and therefore represent a potential therapeutic approach for lupus treatment." (PMID 32528469, 2020). "Another explanation is that the lpr lupus model is based on extensive cell apoptosis, and the apoptosis signaling pathway interacted with the NLRP3 signaling pathway." (PMID 31427885, 2019). "In lupus-prone mice, inhibition of NLRP3 with MCC950 ameliorated proteinuria and renal histologic lesions." (PMID 31871956, 2019). "Pharmacologic inhibition of the NLRP3 inflammasome using P2X7 or NF-κB blockade rescued lupus nephritis in lupus-prone animals." (PMID 31694192, 2019). "BAY 11-7082 improved proteinuria, blood urea nitrogen, and renal inflammation, and ultimately, it decreased mortality in lupus-prone MRL/lpr mice by attenuating NLRP3 inflammasome activation and NF-κB." (PMID 31694192, 2019). "Immune complexes with DNA or RNA antigens directly stimulate the NLRP3 inflammasome or trigger inflammasome activation through TLR-dependent NF-κB signaling in systemic lupus erythematosus." (PMID 31694192, 2019). "Of note, NLRP3 inflammasome activation in podocytes of LN and other cells by lupus immune complex was identified, suggestive of the inflammasome contributing to the development of lupus, including LN." (PMID 31475012, 2019). "It has been shown that NLRP3 inflammasome activation is involved in the pathogenesis of lupus mouse models and in human." (PMID 27250627, 2016). "Immune complexes can trigger the activation of the NLRP3 inflammasome in macrophages from systemic lupus erythematosus (SLE) patients and animal models, leading to cell and tissue damage." (PMID 26584539, 2015). "This suggests that the complexes formed in lupus patients can activate myeloid cells via NLRP3 and thereby reinforce T cell activation." (PMID 24409181, 2013). "Notably, the selective GSK3β inhibitor TDZD-8 effectively blocked NLRP3/IL-1β activation in peripheral blood mononuclear cells from patients with systemic lupus erythematosus." (PMID 40526103, 2025). "Furthermore, GSK3β contributes to lupus nephritis development in lupus-prone mice, in part through activation of the NLRP3/IL-1β axis." (PMID 40526103, 2025). "The P2X7 receptor is involved in systemic lupus erythematosus through the activation of the NLRP3 inflammasome and increased production of IL-1β and IL-18 by lupus patient-derived macrophages, thereby contributing to the cardiovascular, cutaneous, and renal manifestations of lupus." (PMID 41002432, 2025). "In (NZB×NZW)F1 lupus-prone mice, renal NLRP3 inflammasome activation is markedly enhanced." (PMID 41357229, 2025). "In addition, TLR7 and NLRP3 expression was significantly increased in the lupus groups, although it was significantly less pronounced in the CLC group." (PMID 40507090, 2025). "Research conducted in both animal models and humans has demonstrated hyperactivation of the NLRP3 inflammasome in peripheral blood mononuclear cells (PBMCs) and kidney tissue, including podocytes and tubular cells, in individuals with systemic lupus erythematosus (SLE)." (PMID 38740765, 2024). "Furthermore, various drugs that inhibit NLRP3 inflammasome activation attenuate disease severity in different lupus mouse models." (PMID 37081890, 2023). "Similarly, the highly expressed mammalian target of rapamycin (mTOR) in lupus mice has also been shown to induce lupus nephritis (LN) through activation of mTOR/mitochondrial ROS/NLRP3 signaling." (PMID 35693810, 2022). "Activation of the NLRP3 inflammasome resulted in a decrease in lupus development in mice." (PMID 33534121, 2021). "Interestingly, the suppression of NLRP3 inflammasome by curcumin supplementation has also been observed in lupus-prone mice." (PMID 33776996, 2021).
systemic lupus erythematosus (continued). "One study showed that EGCG was able to prevent the development of LN in NZB/WF1 lupus-prone mice due to inactivation of the Nrf2 antioxidant pathway, which resulted in renal NLRP3 inflammasome inactivation with less amounts of IL-1β and IL-18 in kidney lysates." (PMID 34830358, 2021). "In the later stage of SLE, the expression of NLRP3 inflammasome and caspase-1 could be detected in podocytes in murine lupus models." (PMID 34707607, 2021). "When NLRP3 inflammasomes were suppressed with a caspase-1 inhibitor, proteinuria, renal histological lesions and podocyte foot process effacement was found to be ameliorated in lupus-prone mice." (PMID 34867948, 2021). "In Nlrp3-R258W mutant mice, more severe renal pathological changes occurred when intraperitoneal injection with pristane and specific abrogation of Nlrp3-R258W expression in myeloid cells conferred a therapeutic benefit to lupus Nlrp3-R258W mutant." (PMID 34489689, 2021). "Baicalein also inhibited NLRP3 inflammasome activation by decreasing the expression of NLRP3, caspase-1, and IL-1β, the activation of NF-κB by suppressing NF-κB phosphorylation, and the levels of ROS in pristine-induced lupus mice and LPS-stimulated MDSCs." (PMID 33418975, 2021). "NLRP3 inflammasomes in podocytes are activated in lupus-prone mice and also in patients with LN." (PMID 34867948, 2021). "Furthermore, P2X7 has been shown to attenuate murine lupus symptoms by inhibiting the activation of the NLRP3 inflammasome." (PMID 32933004, 2020). "Researches demonstrate that rapamycin reduces NLRP3 inflammasome activation by inhibiting the mTOR/NF-κB pathway in macrophages, and mTOR regulates NLRP3 inflammasome activation via reactive oxygen species in murine lupus." (PMID 33551822, 2020). "Furthermore, NZB mice exhibited an increase in IL-1β and IL-17A concentrations and the Th17/Treg cell ratio following injection of anti-dsDNA antibodies, suggesting that the NLRP3 inflammasome is involved in lupus pathogenesis in mice." (PMID 32528469, 2020). "Lupus-induced renal injuries were ameliorated in mice with myeloid cell-specific deletion of NLRP3." (PMID 31694192, 2019). "Here we determined the changes of Nrf2, NLRP3, or NF-κB in pristane-induced lupus." (PMID 31023362, 2019). "In systemic lupus erythematosus (SLE) pregnancy, neutrophil extracellular traps (NETs) promote glycolysis and lactate production in trophoblasts, leading to NLRP3 lactylation, which subsequently activates the inflammasome and triggers pyroptosis." (PMID 41459510, 2025). "Furthermore, it remains to be seen whether inhibition of the activation of the NLRP3 inflammasome, as recently shown with mesenchymal stem cells in murine and human lupus, has a more favourable efficacy/side-effect profile." (PMID 41436137, 2025). "The NLRP3 inflammasome displays a vital role in the innate and adaptive immune system, as well as its contribution to several autoimmune diseases, including rheumatoid arthritis, systemic lupus erythematosus (SLE), Sjögren’s syndrome, systemic sclerosis, and ankylosing spondylitis." (PMID 39456253, 2024). "Self-dsDNA together with its autoantibodies can trigger the activation of the NLRP3 inflammasome in systemic lupus erythematosus (SLE)." (PMID 37960237, 2023). "Patients with systemic lupus erythematosus (SLE) suffer from disordered Th1/Th2 and Treg/Th17 balances, evidence has demonstrated that NLRP3, NLRP1, NLRC4, and AIM2 were involved in the regulation of Th1, Tfh, and Th17 cell-mediated immune responses." (PMID 38177104, 2024). "EGCG also inhibited NLRP3 inflammasome activation by reducing NLRP3 expression and production of active caspase-1, IL-1β, and IL-18 in NZB/W F1 lupus-prone mice." (PMID 33418975, 2021). "Further research had shown that NLRP3 drove the expression of the TGF-β receptor and downstream molecules which can suppress lupus progression." (PMID 31427885, 2019).
systemic lupus erythematosus (continued). "The kidneys of lupus-prone NZBWF1 mice demonstrated the activation of the NLRP3 inflammasome, and the renal expression of NLRP3 was correlated with the progression of CKD in patients with lupus nephritis." (PMID 31694192, 2019). "Neuronal shrinkage and nuclear chromatin condensation were visible in the hippocampal cornu ammonis and dentate gyrus zones of lupus mice, with an increased expression of TLR7 and NLRP3, versus significantly less neurodegeneration and TLR7 and NLRP3 expression in the CLC group." (PMID 40507090, 2025). "Such opposing observations with us might be explained by the different immunopathogenesis between diseases, as NLRP3-GSDMD-IL-1β axis exerts definite pro-inflammatory effects in MI but not in lupus-like autoimmunity." (PMID 38831451, 2024). "This is in surprising contrast to the role of NLRP3 in a model of lupus-like systemic autoimmunity, where the absence of Nlrp3 and Casp1 accelerated the systemic autoimmune process; NLRP3 is needed to maintain the immunosuppressive effect of TGFβR signaling that counterbalances adaptive immunity." (PMID 37564649, 2023). "Additionally, it has been proven to be effective in inhibiting B cell differentiation into plasma cells in the germinal center of lupus-prone mice, reduction of NLRP3 inflammasome activation mediated by AMPK, and blockade of pyroptosis of tubular epithelial cells in pristane-induced lupus mice." (PMID 35958572, 2022). "However, in the common lpr lupus model, the lack of NLRP3 and ASC did not deliver an expected effect on disease improvement, instead further damaging kidney function and causing exacerbated activation of lymphocytes." (PMID 31427885, 2019). "In contrast, the low expression of the NLRP3 inflammasome in PBMCs from SLE patients might be related to the high expression of type I interferon (IFN-I), which is common in SLE patients and murine models of lupus." (PMID 30202244, 2018). "In addition, the NLRP3/ASC inflammasome protected against kidney damage independent of IL-1 signaling due to regulation of the anti-inflammatory activity of transforming growth factor-β (TGF-β) in C57BL6/Jlpr/lpr mice, which represent a mild spontaneous model of lupus." (PMID 26579125, 2015). "In lupus-prone NZM2328 mice, NLRP3 stimulation in non-myeloid cells, like podocytes, enhanced lupus nephritis progression." (PMID 35204131, 2022).
hepatocellular carcinoma (92 papers, 2014 to 2026). A malignant tumor that arises from hepatocytes. "Dysregulated expression of the NLRP3 inflammasome has been implicated in tumor progression in hepatocellular carcinoma." (PMID 38697992, 2024). "The deletion of NLRP3 in human hepatocellular carcinoma can cause upregulation of MICA/B expression which interacts with the NKG2D receptor in NK-92 cells, resulting in cytotoxicity of NK cells." (PMID 37081882, 2023). "Studies showed that the expression of NLRP3 in hepatocellular carcinoma was significantly downregulated and NLRP3 deficiency was associated with advanced clinical stage and poor pathological differentiation." (PMID 36177050, 2022). "Overall, these experimental results show that NLRP3 is modified by K63-linked ubiquitination in hepatoma cells and that K63-ubiquitination of NLRP3 is decreased during HCV infection." (PMID 34431717, 2021). "Another miRNA which is linked with hepatocellular carcinoma and NLRP3 inflammasome is miR-30e, examined from patients' serum and proposed for diagnosis and anticancer therapeutics." (PMID 33015196, 2020). "The nod-like receptor protein 3 (NLRP3) is one of the most characterized inflammasomes involved in the pathogenesis of several cancers, including hepatocellular carcinoma (HCC)." (PMID 39090420, 2025). "While NLRP3 inflammasome components are upregulated in tissues affected by hepatitis and cirrhosis, their expression is reduced in hepatocellular carcinoma." (PMID 40141358, 2025). "Studies have shown that SRI regulates VEGFA/B expression via the PI3K pathway and negatively modulates pyroptosis by interacting with the NLRP3 inflammasome, thereby promoting hepatocellular carcinoma proliferation." (PMID 40228435, 2025). "One study analyzed the expression of NLRP3 in normal liver tissue and liver tissue from patients with hepatitis, cirrhosis, and hepatocellular carcinoma, representing different stages of hepatocarcinogenesis." (PMID 38182564, 2024). "Eriodictyol exhibits potential for broad application in the treatment of hepatocellular carcinoma due to its ability to suppress hepatocellular carcinoma angiogenesis, motility, cell viability, and tumor growth by deactivating the NLRP3 inflammasome." (PMID 39683630, 2024). "Upregulation of NLRP3 inflammasome components has been detected in tissues of hepatitis and cirrhosis, while the expression levels are diminished in hepatocellular carcinoma." (PMID 36932407, 2023). "Separately, the antitumor drug Alpinumisoflavone was found to suppress the growth and metastasis of hepatocellular carcinoma cells through the induction of pyroptosis in an NLRP3 inflammasome-dependent fashion." (PMID 37885032, 2023). "ANI (Anisodamine or ANI) is an alkaloid extracted from Anisodus) has been suggested to promote apoptosis by suppressing the NLRP3 inflammasome in the HepG2 hepatoma cell line and HCC rodent model." (PMID 38143439, 2023). "Our study establishes that the NLRP3 inflammasome complex, which can induce proinflammatory cytokine IL-1β production, is assembled and activated in human hepatoma cells." (PMID 34431717, 2021). "Our study focuses on understanding PTMs leading to activation of the NLRP3 inflammasome during HCV infection of human hepatoma cells." (PMID 34431717, 2021). "A previous study showed that miR-223 inhibited hep3B (hepatocellular carcinoma cell line) cell proliferation and promoted apoptosis by directly targeting NLRP3 (NOD-like receptor family, pyrin domain containing 3)." (PMID 32873229, 2020). "NLRP3 inflammasome constituents are significantly down-regulated in human hepatocellular carcinoma (HCC) as compared to inflamed and normal hepatic tissues." (PMID 33014808, 2020). "In hepatocellular carcinoma, a negative regulator of NLRP3 inflammasome, miR-223, was found to be present in high expression levels, which were associated with posttranscriptional mechanisms and proliferation of tumor cells." (PMID 33015196, 2020).
hepatocellular carcinoma (continued). "This is not consistent with a previous report that estrogen up-regulates NLRP3 via ERβ mediation in hepatocellular carcinoma cells." (PMID 30373775, 2019). "17β-estradiol (E2)-induced activation of the NLRP3 inflammasome triggered pyroptotic cell death and suppressed protective autophagy in hepatocellular carcinoma (HCC) cells." (PMID 31492049, 2019). "NLRP3 inflammasome-dependent pyroptosis has been described in HCV-infected hepatoma cells, Dengue virus (DV)-infected monocytes, and HIV-infected podocytes." (PMID 29163496, 2017). "It was very recently shown that NLRP3 is repressed in human hepatocellular carcinoma compared to healthy liver cells, and that NLRP3 expression inversely correlates with liver cancer progression." (PMID 27221966, 2016). "Furthermore, the upregulation of NLRP3 by 17 β‐estradiol inhibited the growth of hepatocellular carcinoma cells." (PMID 40671401, 2025). "NLRP3 plays a similar antitumor role in hepatocellular carcinoma patients." (PMID 40671401, 2025). "We further demonstrated that histone H3 could also promote proliferation and metastasis of hepatocellular carcinoma through TLR9 activation of NLRP3 inflammasome." (PMID 37082731, 2023). "The overexpression of NLRP3 by 17β-estradiol (E2) inhibits the development of hepatocellular carcinoma cells, indicating that NLRP3 may play a protective function in hepatic malignancy." (PMID 37715239, 2023). "On the contrary, NLRP3 inflammasome was downregulated in human hepatocellular carcinoma, and the absent NLRP3 was linked to advanced stages." (PMID 37304662, 2023). "However, it has also been reported that E2 significantly inhibited the malignant behaviors of hepatocellular carcinoma cells through E2/ERβ pathway-mediated upregulation of the NLRP3 inflammasome." (PMID 35694250, 2022). "However, in hepatocellular carcinoma tissues, the expression of NLRP3 has been shown to be negatively correlated with the pathological grade and clinical stage, suggesting that apoptosis inhibits the further development of tumors." (PMID 35846123, 2022). "Furthermore, after ROSs and NLRP3 inflammatory corpuscles were activated, the secretion of IL-1β was promoted, and the rates of proliferation, migration, and invasion of hepatoma cells were accelerated." (PMID 35095920, 2021). "Another study demonstrated that the NLRP3 inflammasome expression signal in normal, hepatitis-related, and cirrhotic tissue shows a continuously increasing trend; however, it becomes significantly reduced in hepatoma tissues." (PMID 32347316, 2020). "NLRP3 inflammasome-mediated pyroptosis is also observed in DV-infected monocytes and in HCV-infected and bystander hepatoma cells, and could be associated with viral pathogenesis." (PMID 29163496, 2017). "A protective role for NLRP3 has also been described in hepatocellular carcinoma (HCC)." (PMID 25071785, 2014). "Indeed, in contrast to our study, estrogens were reported to inhibit NLRP3 inflammasome pathway activation, caspase-1, and proinflammatory cytokine production in the brain after global cerebral ischemia, while activating NLRP3 inflammasome and triggering pyroptosis in hepatocellular carcinoma cells." (PMID 39654901, 2024). "In 2020, Chen and colleagues elucidated a mechanism by which IRAK1 promotes metastasis in hepatocellular carcinoma (HCC) through the activation of the NLRP3/MAPKs/IL-1β pathway." (PMID 39451208, 2024). "Opposite evidence derives from a study on hepatocellular carcinoma (HCC) where NLRP3 has been reported to be involved in cancer development." (PMID 35095876, 2021). "For example, alpinumisoflavone (AIF) inhibited hepatocellular carcinoma (HCC) cell metastasis by promoting NLRP3 inflammasome-mediated pyroptosis, suggesting pyroptosis inhibited cell metastasis in AIF-treated HCC cells." (PMID 34381023, 2021).